TLR4 (toll like receptor 4)
Diseases named in the same sentence as TLR4 in open-access papers (continued):
Sharing a sentence is not in itself a finding about the gene and the disease.
liver fibrosis (continued). "TLR4 signalling has been shown to be critical to the development of hepatic fibrosis in several experimental models." (PMID 20161726, 2010). "Therapies aimed at suppressing TLR4 signalling, either through preventing LPS release or TLR4 inhibition, is already being considered in the context of hepatic fibrosis, although other fibrotic targets are also under investigation." (PMID 19961576, 2009). "Impaired TLR4 and nine responses through defective signalling, and also the presence of genetic variations, have been shown to reduce hepatic fibrosis." (PMID 19961576, 2009). "Additionally, BSP exhibits the ability to alleviate hepatic fibrosis through the TLR2/TLR4-MyD88-NF-κB signaling pathway, ultimately achieving hepatic protection." (PMID 40626309, 2025). "Furthermore, through activation of signaling pathways such as LPS/TLR4, cGAS/STING, and TGF-β, BEVs promote the progression of metabolism-associated fatty liver disease (MAFLD), liver fibrosis, and hepatocellular carcinoma." (PMID 40621163, 2025). "Moreover, isochlorogenic acid A was reported to improve liver fibrosis and inflammation by inhibiting toll-like receptor 4 (TLR4)/NF-κB pathways." (PMID 41471340, 2025). "TLR4 plays a pivotal role in the inflammatory response during liver fibrosis." (PMID 39979806, 2025). "Moreover, the gut microbiota can recruit DNA methyltransferase 3 (DNMT3) to induce epigenetic modifications of Toll-like receptor 4 (TLR4) in intestinal epithelial cells, thereby impacting hepatic fibrosis and steatosis." (PMID 40809055, 2025). "BSP can improve liver fibrosis by regulating the TLR2/TLR4-MyD88-NF-κB signaling pathway." (PMID 40626309, 2025). "Indeed, TLR4 signaling plays a key role in activated HSCs, which represent the major fibrogenic cell type during liver fibrosis." (PMID 39683940, 2024). "Apart from TLR4, there is some evidence about the involvement of other TLRs in liver fibrosis." (PMID 39201329, 2024). "TLR, especially the TLR4 signalling pathway, plays a crucial role in liver fibrosis." (PMID 39031798, 2024). "TLR4 antagonist Sparstolonin B (SsnB) inhibited TLR4-induced liver fibrosis." (PMID 38192427, 2023). "This study examined whether EPO affects thioacetamide (TAA)-induced liver fibrosis by concentrating on the Toll-like receptor 4 (TLR4) cascade and the phosphatidylinositol 3-kinase (PI3K)/Akt pathway as possible pathways." (PMID 37649466, 2023). "Along the same line, TLR4 signaling regulates the immune response in mice models of liver fibrosis." (PMID 37345131, 2023). "Then LPS acts on TLR4 in liver through the “gut-liver” axis, activating intracellular downstream signaling pathways, and ultimately contributing to liver inflammation and progression of liver fibrosis." (PMID 36579341, 2022). "In addition, TLR4 stimulation also promotes liver fibrosis by downregulating the expression of Bambi, an endogenous decoy receptor for the TGF-β receptor, and upregulating the TGFβ/Smad signaling pathway." (PMID 36189347, 2022). "This suggested that chronic psychological stress was involved in the activation of the TLR4 signaling pathway in the liver, which may damage the liver and promote the progression of liver fibrosis through the TLR4 signaling pathway." (PMID 36579341, 2022). "TLR4 protein expression in the liver fibrosis group was significantly increased, and after rats with liver fibrosis were exposed to chronic psychological stress, TLR4 protein expression was further increased compared with the liver fibrosis group." (PMID 36579341, 2022). "The TLR family are transmembrane proteins on intrahepatic cells that activate the innate immune system by recognizing microbiota and metabolites from the intestine, of which, TLR2, TLR4, TLR5, TLR7, and TLR9 can be involved in liver fibrosis, with TLR4 currently being the most studied." (PMID 36189347, 2022).
liver fibrosis (continued). "Quiescent HSCs highly express BAMBI (bone morphogenetic protein and activin membrane bound inhibitor), but their transcriptional activity is inhibited after LPS treatment, which contributes to TLR4-mediated enhancement of transforming growth factor (TGF)-β signalling in HSCs during liver fibrosis." (PMID 35572649, 2022). "In the present study, we demonstrated that S100A8 as a crucial DAMP could stimulate NLRP3 inflammasome-dependent pyroptotic macrophage death by activating TLR4-dependent NF-κB and inducing ROS abundance, finally facilitating liver fibrosis progression." (PMID 36429008, 2022). "The lncRNA MALAT1 promotes liver fibrosis by targeting the miR-181a/TLR4/NF-κB axis." (PMID 35890132, 2022). "Consistent with the results of previous animal studies, the investigation of the cell insulin signaling pathway suggested that the H-L + HFD-induced liver fibrosis was mediated by gut microbiota through disruption of the gut barrier TLR4/MYD88 and liver IRS1/Akt/mTOR signaling pathways." (PMID 36204709, 2022). "For example, alcohol could increase intestinal permeability, thus the level of LPS in the circulation is enhanced and activates HSCs and KCs in liver through TLR4 signaling pathway, which lead to the progression of liver fibrosis." (PMID 35990625, 2022). "Another study showed that uric acid increases the hepatic stellate cells by activating inflammatory mediators including Toll-like receptor-4, Monocyte Chemoattractant Protein-1 and Cluster of Differentiation 68 mRNA expression in the liver, ultimately leading to liver fibrosis." (PMID 35813625, 2022). "Therefore, we tested the expression levels of HMGB1, TLR4, Myd88, and NF-κB p65, which are the key targets of this signaling pathway in liver fibrosis rats." (PMID 33790974, 2021). "We previously showed that TLR4 signaling in HSCs correlated with liver fibrosis after Sj infection." (PMID 34034779, 2021). "Furthermore, the degree of liver fibrosis in TLR4 mutant mice was lower than that in TLR4 wild‐type mice after eight doses of CCl4 administration." (PMID 33336563, 2021). "The RNA interference‐mediated TLR4 gene silencing might be a potential therapeutic approach for liver fibrosis." (PMID 33336563, 2021). "Accordingly, we performed our liver fibrosis models using TLR4 KO mice." (PMID 33391458, 2021). "We have shown that oral IAP could represent a novel therapy to prevent the development of liver fibrosis by detoxifying luminal LPS and protecting the gut barrier function, in a TLR4-dependent fashion." (PMID 33391458, 2021). "Our work aimed to investigate the role of the COX2/PGE2 axis in Sj-induced liver fibrosis and to determine whether the relationship between it and TLR4 signaling is the mechanism." (PMID 34034779, 2021). "To determine whether the TLR4 pathway regulates the COX2/PGE2 axis during Sj infection-induced liver fibrosis, we examined the levels of several key proteins in this axis using infected mice liver after TAK242 treatment." (PMID 34034779, 2021). "Besides, the administration of andrographolide inhibited the TLR4 expression and ameliorated the CCl4‐induced liver fibrosis in mice." (PMID 33336563, 2021). "Also, mogroside IVE mediated down‐regulation of the TLR4 signalling pathway inhibited the activation of HSCs and attenuated liver fibrosis in mice." (PMID 33336563, 2021). "Interestingly, recent findings suggest that TLR4 plays a crucial role in liver fibrosis progression, and inhibition of the TLR4 signalling pathway alleviates liver injury, which in turn attenuates liver fibrosis." (PMID 33336563, 2021). "Also, the VitA‐lip‐TLR4‐shRNA distribution in the lungs of the mice with liver fibrosis was significantly less than the lungs of normal mice." (PMID 33336563, 2021).
liver fibrosis (continued). "As the TLR4 mediates inflammatory and pro‐fibrogenic signalling in HSC, the development of safe and efficient shRNA delivery vehicles targeted against the TLR4 to mitigate their signalling might serve as an efficient therapeutic agent for liver fibrosis." (PMID 33336563, 2021). "It is reported that the binding of extracellular HMGB1 to TLR4 could activate NF-κB signaling to induce inflammation and aggravate liver fibrosis." (PMID 33790974, 2021). "We also provide evidence of TLR4 signaling activation of the COX2/PGE2 axis that might contribute to mice liver fibrosis induced by Sj infection." (PMID 34034779, 2021). "The activation of the TLR4 signalling pathway plays a crucial role in liver fibrosis." (PMID 33336563, 2021). "A pathway that seems exclusive to liver fibrosis comprises Toll-like receptor 4 (TLR4)." (PMID 34361064, 2021). "JMJD2D, or KDM4D, was recently reported as a remarkable overexpressed H3K9me2/3 demethylase during HSCs activation, it epigenetically facilitates TLR4 gene transcription and thus activates TLR4/NF-kB signaling pathways, promotes HSCs activation and hepatic fibrosis progression." (PMID 33391480, 2021). "TLR4 is the receptor of LPS, LPS/TLR4 signaling in HSCs is essential for development of liver fibrosis and acts via stimulating production of chemokines that recruit KCs alongside enabling unrestricted activation of HSCs by KCs-derived profibrogenic cytokine TGF-beta." (PMID 33933107, 2021). "TLR4 also is shown to induce transforming growth factor β (TGFβ) signaling pathway, activate hepatic stellate cell and increase extracellular matrix deposition, which all contribute to the progression of liver fibrosis." (PMID 32850884, 2020). "Also reduced was the mRNA and protein expression of the pattern recognition receptor TLR4, which is a central event in the progression of hepatic fibrosis." (PMID 32283542, 2020). "Therefore, the inhibition of TLR4 seemed be a prospective strategy for the therapy of hepatic fibrosis." (PMID 32425800, 2020). "Taken together, our study indicated that ICQA could protect against CCl4-induced liver fibrosis probably through suppressing the HMGB1/TLR4/NF-κB signaling pathways." (PMID 32425800, 2020). "attenuated liver fibrosis through antagonizing TLR4 induced TGF-β signaling." (PMID 32477116, 2020). "In addition, Wnt2b, serves as an endogenous inhibitor of TLR4 signaling, exhibited an inhibition on the HSCs activation and mitigated liver fibrosis." (PMID 32425800, 2020). "Activation of TLR4 enhances TGF-β signaling in the development of hepatic fibrosis." (PMID 31068809, 2019). "Indeed, sensing lipopolysaccharide (LPS) by liver parenchymal cell-specific TLR4 contributes to liver fibrosis and HCC." (PMID 30990169, 2019). "TLR4, a molecule contributing to the progression of hepatic fibrosis, can be activated by LPS." (PMID 31719209, 2019). "In addition, it indicates that gut microflora-derived endotoxin and TLR4 contribute to the progression of liver fibrosis." (PMID 31726747, 2019). "This study will evaluate several parameters: nutritional, functional, physical, and laboratorial assessments, including tests used for diagnosis and follow-up (TLR-4 and CK-18), and evaluation of degree of liver fibrosis, intestinal permeability, microbiota composition, and cardiovascular risk." (PMID 31601229, 2019). "Chimeric mice with TLR4 wild-type HSCs and TLR4 mutant Kupffer cells are more sensitive to chemically-induced liver fibrosis compared with TLR4 mutant C3H/HeJ mice and those mice with TLR4 mutant HSCs, but wild-type TLR4 Kupffer cells, indicating the crucial role of TLR4 expression in HSCs12." (PMID 29348414, 2018). "Furthermore, a nucleotide variation in the TLR4 gene brought about protection against the progression of liver fibrosis in humans." (PMID 29743985, 2018). "The induction of mild liver fibrosis was due to activation of the TLR4 pathway." (PMID 30054551, 2018).
liver fibrosis (continued). "Administration of palmitate alone in BD-fed mice caused inflammatory cell infiltration and liver fibrosis mediated by the toll-like receptor 4 pathway without ALT elevation." (PMID 30054551, 2018). "NF-κB p50 is downstream of TLR4 and involved in the liver fibrosis." (PMID 29743985, 2018). "It was shown that a highly significant positive correlation involved TLR4 expression, the progression of liver fibrosis, age, RNA, transaminases, total bilirubin and prothrombin time, and a highly significant negative correlation with platelet count and serum albumin." (PMID 29379592, 2017). "Collectively, the results demonstrate that a miR-29b-3p/HMGB1/TLR4/NF-κB signaling pathway, which can be modulated by CA, is important in liver fibrosis, and indicate that CA might be a prospective therapeutic drug for liver fibrosis." (PMID 29403377, 2017). "Thus, both TGM2 and activation of the TLR4 signal pathway correlated with the development of liver fibrosis during Sj infection." (PMID 29321784, 2017). "In particular, TLR4 plays a crucial role in hepatic inflammation and liver fibrosis." (PMID 29403377, 2017). "Our data demonstrate that Wnt2b may serve as a novel endogenous suppressor of TLR4 signaling-mediated liver fibrosis." (PMID 28638086, 2017). "TLRs, especially TLR4 signal pathway, play critical roles in liver fibrosis." (PMID 29321784, 2017). "Moreover, liver fibrosis was more difficult to be induced in TLR4−/− mice than in WT mice, characterized by lower deposition of collagen." (PMID 28638086, 2017). "The HMGB1/TLR4/NF-κB signaling pathway induces the proliferation, migration and pro-fibrotic effects of HSCs and enhances the related collagen expression and pro-fibrotic cytokine production in liver fibrosis." (PMID 29403377, 2017). "The functional significance of miR-146a-5p during the LPS/TLR4 mediated hepatic fibrosis process remains unclear." (PMID 27399683, 2016). "The mechanism of LPS increased hepatic fibrosis is by increasing the expression of TLR4." (PMID 27776340, 2016). "Importantly, LPS can enormously induce HSCs activation and aggravate liver fibrosis through TLR4 pathway, which has been proved to be an important mechanism in liver injury." (PMID 27776340, 2016). "However, new negative regulators (even blocking agents) of the TLR4-triggered inflammatory response should be further found in the immune cells, especially for treatment of inflammatory disease and hepatic fibrosis." (PMID 26785354, 2016). "In addition, it is postulated that TLR4 and gut microflora-derived LPS contribute to the progression of liver fibrosis." (PMID 27682116, 2015). "Overwhelming endotoxin may activate TLR4 on the hepatic stellate cell, which enhances the production of extracellular matrix and liver fibrosis." (PMID 27682116, 2015). "Importantly, in a mouse model of cholestatic liver injury, the intestinal bacterial microbiota has been shown to drive hepatic fibrosis via TLR4-dependent activation of KCs and alcohol induced liver injury was strongly reduced in Tlr4 mutant mice." (PMID 25329595, 2014). "TLR4 modulated liver fibrosis via a TGF-β-dependent manner in three different models of hepatic disease, suggesting that TLR4 may function as a molecular link between pro-inflammatory and pro-fibrogenic signals in liver." (PMID 24842252, 2014). "TLR4 signaling in HSCs is critical for development of liver fibrosis." (PMID 22973518, 2012). "Notably, endotoxin seems to promote liver fibrogenesis by stimulating TLR4, as elegantly shown in three different mouse models of liver fibrosis." (PMID 20353583, 2010). "HSCs, central cell types in liver fibrosis, also express high levels of TLR4." (PMID 20706677, 2010). "Taken together, TLR4 signaling is crucial in the activation of HSCs during liver fibrosis." (PMID 20706677, 2010). "Intestinal microflora is a major source of LPS as a ligand for TLR4 in liver fibrosis." (PMID 20706677, 2010).
liver fibrosis (continued). "TLR4 and its ligands mediate their effects in liver fibrosis through different mechanisms." (PMID 20964825, 2010). "Furthermore, genetic testing for TLR4 and IL17 polymorphisms may help predict the progression of MASLD by identifying individuals with a higher or lower risk of liver fibrosis." (PMID 40332363, 2025). "Therefore, the inhibition of TLR4-related intracellular signaling may be effective in reducing TLR4-mediated inflammation and potentially inhibit liver fibrosis." (PMID 39063116, 2024). "In summary, SP has an ameliorative effect on hepatic fibrosis, probably by inhibiting the activation of hepatic stellate cells, reducing the synthesis of extracellular matrix by down-regulated the protein expression of toll like receptor 4 (TLR4) and nuclear factor-K b (NF-κB) p65." (PMID 39359922, 2024). "In vitro experiments demonstrated that quercetin treatment led to decreased expression of TGF-β1, α-SMA, HMGB1, TLR2/TLR4, and NF-κB p65 proteins in COL1α1 mRNA, suggesting that quercetin may inhibit HSCs activation and improve liver fibrosis by modulating the HMGB1/TLR/NF-κB signaling pathway." (PMID 39185304, 2024). "Among them, Toll-like receptor 4 (TLR4) has been proven to play a vital role in a variety of diseases such as cancers, cardiovascular diseases, and, especially, pathological conditions in the liver including liver inflammation, hepatic steatosis, and liver fibrosis." (PMID 38137182, 2023). "There are many possible mechanisms for IH to induce liver fibrosis, including via oxidative stress, hypoxia inducible factor mediated inflammation, induction of the TLR4/MAPK/NF-kB pathways, and while this study is not designed to be mechanistic, our findings may inform future studies." (PMID 38077744, 2023). "Furthermore, artesunate could alleviate inflammation-induced liver fibrosis by inhibiting the LPS/TLR4/NF-κB signaling pathway in rats." (PMID 35625074, 2022). "Therefore, inhibition of TLR4-related intracellular signaling may be effective in reducing TLR4-mediated inflammation and inhibiting liver fibrosis." (PMID 35222022, 2022). "Furthermore, TLR4 activation leads to inhibition of tumor necrosis factor alpha, and as TLR4 is expressed on Kupffer cells and hepatic stellate cells, this receptor becomes a significant mediation in hepatic fibrosis." (PMID 35897739, 2022). "Moreover, TFAS decreased the expression of both PAR1 and TLR4 that were induced by liver fibrosis." (PMID 34045968, 2021). "Interestingly, the depletion of intestinal bacteria by a cocktail of antibiotics or blockade of the lipopolysaccharides (LPS)-TLR4 pathway rescues liver fibrosis in murine models 5, thereby implicating the importance of the microbiome and microbial products in the development of this disease." (PMID 33391458, 2021). "Besides, as evident from the outcome of this study, the TLR4 gene silencing inhibited the HSCs activation and attenuated the liver fibrosis via the NF‐κB transcriptional inactivation, pro‐inflammatory cytokines secretion and reactive oxygen species (ROS) synthesis." (PMID 33336563, 2021). "Similarly, prevention of liver fibrosis with CGA administration in CCl4-intoxicated rats is also connected with anti-inflammatory properties of this phenolic compound due to the inhibition of the TLR4/NF-κB signaling pathway." (PMID 34836410, 2021). "Thus, prevention and reversal of TLR4 mediated HSCs activation might serve as an effective therapeutic strategy in the management of liver fibrosis." (PMID 33336563, 2021). "Thus, the VitA‐coupled liposomes encapsulated with the TLR4‐shRNA might prove as an efficient therapeutic agent for liver fibrosis." (PMID 33336563, 2021). "Moreover, miR-146a-5p is known to attenuate liver fibrosis through the regulation of fibrosis-associated pathways, such as TGF-β/SMAD, Wnt/β-catenin, LPS/TLR4/NF-κB, and PTPRA-SRC." (PMID 34796180, 2021). "Thus, high serum levels of TLR4 are considered as a bio-marker for liver fibrosis development." (PMID 32850884, 2020).